FGF23 (fibroblast growth factor 23)
Diseases named in the same sentence as FGF23 in open-access papers (continued):
Sharing a sentence is not in itself a finding about the gene and the disease.
pulmonary hypertension (6 papers, 2021 to 2025). Increased pressure within the pulmonary circulation due to lung or heart disorder. "Fibroblast growth factor-23 (FGF-23) has demonstrated a strong association with RV dysfunction in both HFrEF and pulmonary hypertension, independently of congestion or BNP levels, and was associated with a risk of adverse outcomes." (PMID 41009628, 2025). "This study analyzed the utility of FGF-23 as a biomarker of RV function in patients with pulmonary hypertension (PH)." (PMID 36790465, 2023). "Another postulated pathological mechanism for pulmonary hypertension is an increase in fibroblast growth factor-23 (FGF-23) concentration, which is observed in the course of CKD." (PMID 34829511, 2021). "It remains to be investigated whether FGF-23 is a marker of RV dysfunction specific for HFrEF or if it reflects RV dysfunction in other clinical scenarios (HFpEF, pulmonary artery hypertension)." (PMID 37749114, 2023). "In a limited group of pulmonary hypertension (PHT) patients (n = 48), FGF23 levels exhibited correlations with mean pulmonary artery pressure (mPAP), cardiac index (CI), pulmonary vascular resistance (PVR), NT-proBNP and the REVEAL risk score." (PMID 40863356, 2025).
Raine syndrome (6 papers, 2015 to 2025). "It was not possible to measure the plasma FGF23 values of the families described in this study, although FGF23 has been persistently described as raised in some individuals with non-lethal Raine syndrome." (PMID 25928877, 2015).
aortic stenosis (5 papers, 2023 to 2026). Aortic valve stenosis is a aortic valve disease caused by the incomplete opening of the aortic valve. "We observed that for a lead variant near FGF23, rs10744645, the C allele was associated with a greater risk of aortic stenosis." (PMID 41419685, 2026). "These novel findings suggest a novel role of FGF23 in the pathogenesis of CAVD associated with CKD and point to the therapeutic potential of Klotho for prevention of CAVD development and progression in old CKD subjects with high risks for CAVD and aortic stenosis." (PMID 38993571, 2024). "In this observational study, FGF-23 was measured in the plasma of patients with PH (n = 627), dilated cardiomyopathy (DCM, n = 59), or LVH with severe aortic stenosis (n = 35)." (PMID 36790465, 2023).
aortic valve calcification (5 papers, 2018 to 2024). "This is supported by a study reporting a positive association between aortic valve calcification and serum FGF23 levels in patients with CKD." (PMID 29922171, 2018). "Additionally, high levels of P and FGF-23 were also found as independent risk factors for mitral valve calcification (ORa = 1.078, p = 0.001; ORa = 1.209, p = 0.035), and aortic valve calcification (ORa = 1.497, p = 0.002; ORa = 1.126, p = 0.011)." (PMID 35204586, 2022). "Furthermore, FGF23 induces the expression of osteoblastic biomarkers and promotes calcium deposition in AVICs, contributing to the mechanism of aortic valve calcification." (PMID 38993571, 2024). "FGF-23 participates in activated vitamin D circulating levels reduction, and an association between increased FGF-23 and reduced Klotho with vascular calcification and aortic valve calcification in CKD patients was previously reported." (PMID 34945764, 2021).
autoimmune disease (5 papers, 2018 to 2026). A disorder resulting from loss of function or tissue destruction of an organ or multiple organs, arising from humoral or cellular immune responses of the individual to their own tissue constituents. "In autoimmune diseases, fibroblast growth factors (FGFs) and their receptors play key roles in inflammatory responses and tissue repair, such as FGF-23, which promotes pro-inflammatory responses of M1 macrophages during infections." (PMID 39104791, 2024). "The genes related to the development of autoimmune disorders were also analyzed because of the case report of autoimmune tumoral calcinosis due to spontaneously developed anti-FGF23 neutralizing antibody." (PMID 34901334, 2021). "Similarly, the expression of Fgf23 mRNA was reduced by the synthetic glucocorticoid prednisolone that is also widely used in the treatment of autoimmune diseases." (PMID 33517471, 2021).
colorectal cancer (5 papers, 2011 to 2026). A primary or metastatic malignant neoplasm that affects the colon or rectum. "FGF23 is highly expressed in prostate and colorectal cancer, and colorectal cancer with high FGF23 expression is prone to calcium and phosphorus metabolism disorders." (PMID 36604721, 2023). "The plasma FGF23 concentration may rise in colorectal adenoma, and FGF23 excretion is enhanced in the stool from patients with colorectal carcinoma (Wang H.-P." (PMID 33520985, 2020).
dilated cardiomyopathy (5 papers, 2018 to 2025). Cardiomyopathy which is characterized by dilation and contractile dysfunction of the left and right ventricles. "Richter and colleagues find that FGF23 is present in cardiac myocytes of patients with ischemic cardiomyopathy, myocarditis, and dilated cardiomyopathy." (PMID 29892269, 2018). "Enhanced cardiac FGF23 is reported in various clinical and experimental settings of cardiac remodeling or failure, e.g., CKD, ADHF, ischemic cardiomyopathy, myocarditis, dilated cardiomyopathy, inflammatory HF, TAC-induced pressure overload, experimental MI, and ischemia reperfusion in rodents." (PMID 29892269, 2018).
emphysema (5 papers, 2018 to 2022). "A genetic variant associated with low FGF23 was found to be associated with emphysema in smokers with COPD." (PMID 29766437, 2018).
fractures (5 papers, 2012 to 2023). "The MrOS study showed prospectively that FGF23 levels higher than 55.7 pg/ml are associated with an increased risk of hip and nonvertebral fractures and that FGF23 levels higher than 57.4 pg/ml are associated with an increased risk of vertebral fracture." (PMID 23013306, 2012). "In this study, we investigated the prevalence of vertebral fracture that occurred within five years in predialysis CKD patients and whether FGF23 level is associated with vertebral fracture." (PMID 23013306, 2012).
gestational diabetes (5 papers, 2017 to 2024). Carbohydrate intolerance first diagnosed during pregnancy. "This study was designed to compare the serum levels of fibroblast growth factor 23 (FGF23) among patients with gestational diabetes mellitus (GDM) and healthy pregnant women, and to evaluate the association between hormonal and metabolic parameters." (PMID 28977159, 2017). "In patients with gestational diabetes, FGF-23 may be a promising indicator of subclinical arteriosclerosis, and FGF-23 has previously been shown to be positively correlated with the development of coronary atherosclerosis." (PMID 32998751, 2020). "In conclusion, the present prospective study is the first in the literature that evaluated the relationship between FGF-23 and MPI in patients with gestational diabetes in the absence of CVD." (PMID 30462803, 2018).
hyperlipidemia (5 papers, 2018 to 2025). "Positive associations between circulating FGF-23 levels and hepatic steatosis, adiposity, and circulating hyperlipidaemia have been described and therefore following weight loss intervention withdrawal, a differential impact on circulating FGF-23 levels could have a metabolic impact." (PMID 40342635, 2025).
hyperthyroidism (5 papers, 2012 to 2025). Overactivity of the thyroid gland resulting in overproduction of thyroid hormone and increased metabolic rate. "Control of other endocrinopathies, including hyperthyroidism, growth hormone excess, and phosphate wasting secondary to fibroblast growth factor 23 (FGF23) overproduction is equally critical." (PMID 41300813, 2025). "Other differential considerations include granulomatous diseases (e.g., sarcoidosis, tuberculosis, infections), vitamin D-related disorders, hyperthyroidism, medication effects, FGF23-related disorders, and genetic conditions such as familial hypocalciuric hypercalcemia (FHH)." (PMID 41287694, 2025). "Plasma FGF-23 concentrations were higher in pre-azotemic cats than nonazotemic cats and increased following the treatment of hyperthyroidism.d FGF-23 was also evaluated prospectively in nonazotemic cats." (PMID 23566108, 2013). "FGF-23 has been measured in cats with CKD and hyperthyroidism and is discussed later." (PMID 23566108, 2013).
hypophosphatasia (5 papers, 2021 to 2022). Hypophosphatasia (HPP) is a rare heritable metabolic disorder characterized by defective mineralization of bone and/or teeth in the presence of reduced activity of unfractionated serum alkaline phosphatase (ALP). "PPi may regulate the FGF23 production: however, patients with hypophosphatasia, the disease caused by inactivating mutations in tissue non-specific alkaline phosphatase, have normal FGF23 levels along with elevated PPi levels." (PMID 36246908, 2022). "While entirely unanticipated, our data does demonstrate variably high serum intact FGF23 levels in this murine model of severe infantile hypophosphatasia and that high serum FGF23 correlates with severity of the phenotype." (PMID 35909501, 2022). "Questions remain in regards to if the FGF23 is a cause, consequence or simply a marker of phenotype severity in the TNAP−/− mice, and if FGF23 may also be relevant to lethal perinatal and/or infantile human hypophosphatasia." (PMID 35909501, 2022). "The results also show that FGF23 rises in the TNAP−/− model of murine lethal hypophosphatasia." (PMID 35909501, 2022). "We also tested serum FGF23 levels in younger mice, because day 17 TNAP null mice already have a severe hypophosphatasia phenotype." (PMID 35909501, 2022).
ischemia (5 papers, 2015 to 2025). A hypoperfusion of the BLOOD through an organ or tissue caused by a PATHOLOGIC CONSTRICTION or obstruction of its BLOOD VESSELS, or an absence of BLOOD CIRCULATION. "The authors additionally suggested that increase in FGF-23 during hospitalization could be associated with peripheral production in bone and kidney due to prolonged ischemia." (PMID 39941530, 2025). "Nevertheless, LAD ligation inevitably causes HF; hence, it is still unclear whether cardiac FGF23 expression was mainly triggered by ischemia or rather by the loss of cardiac function." (PMID 35160052, 2022).
phosphorus metabolism disorders (5 papers, 2020 to 2024). "Tumor patients with high FGF23 expression who develop calcium and phosphorus metabolism disorders is more likely to exacerbate the deterioration of the disease." (PMID 36604721, 2023).
Ventricular arrhythmia (5 papers, 2021 to 2026). "The action potential plateau of ventricular muscle is longer than that of atrial muscle cells, and FGF23 may be more likely to cause repolarization‐related Ventricular arrhythmia." (PMID 40126903, 2025). "Therefore, our results suggest that the vulnerability to ventricular arrhythmias at early and longer term after I/R injury might be explained, at least in part, by the elevated and maintained circulating FGF-23 levels." (PMID 35216382, 2022).
alcohol (4 papers, 2021 to 2025). "Regular bone health assessments, including monitoring antioxidants such as glutathione peroxidase, FGF23 levels, and bone remodeling markers like RANKL, could be beneficial for early detection and intervention in alcohol-induced bone loss." (PMID 39062088, 2024). "In conclusion, we report that activated CB1 receptor induced ERRγ expression leads to hepatic FGF23 expression, which in turn up-regulates CYP2E1 expression and thereby exacerbates chronic alcohol-induced liver injury in mice." (PMID 38479224, 2024).
arteriosclerosis (4 papers, 2012 to 2020). A vascular disorder characterized by thickening and hardening of the walls of the arteries. "Both, Fgf23-deficient (Fgf23−/−) and klotho (kl−/−) deficient mice, show a similar phenotype displaying growth retardation, growth plate abnormalities, highly elevated serum phosphate and serum 1,25D3 levels, infertility, arteriosclerosis, premature aging and a shortened lifespan." (PMID 22242193, 2012).
asthma (4 papers, 2017 to 2026). "Additionally, the ACS-NSQIP did not record some relevant information such as echocardiography, pulmonary function test, serum levels of FGF23 and 25-hydroxyvitamin D, pleural effusion, obstructive sleep apnea, and asthma." (PMID 28747700, 2017).
biliary atresia (4 papers, 2018 to 2025). A rare, biliary tract disease characterized by progressive obliterative cholangiopathy of the intra- and extrahepatic bile ducts, occurring in the embryonic/ perinatal period, leading to severe and persistent neonatal jaundice and acholic stool. "On the contrary, in patients with TIO, the responsible tumors produce FGF23 and FGF23 is shown to be expressed in liver in a patient with biliary atresia." (PMID 29515522, 2018).
cardioembolic stroke (4 papers, 2018 to 2023). "Fibroblast growth factor-23 also has been associated with an increased risk of cardioembolic stroke." (PMID 36837457, 2023). "A relationship has only been demonstrated between FGF-23 and haemorrhagic stroke and FGF-23 and cardioembolic stroke, however." (PMID 33767635, 2021).
chronic lung disease (4 papers, 2021 to 2025). According to the definitions of the American and British Thoracic Societies, including pulmonary functional tests, X-rays, and CT scans for items such as fibrosis, bronchiectasis, bullae, emphysema, nodular or lymphomatous abnormalities. "Chronic lung diseases such as COPD and idiopathic pulmonary fibrosis have been associated with FGF23." (PMID 39936727, 2025). "In vitro and animal studies indicate that FGF23 acts as a deleterious agent by enhancing lung inflammation in various chronic lung diseases." (PMID 37637614, 2023). "Despite this being a “negative” study, it is of importance to further characterize FGF23 and its pleiotropic effects in different lung cells and different chronic lung diseases." (PMID 37763754, 2023). "Extensive in vitro and animal studies show that FGF23 acts as a harmful agent by promoting inflammation of the lung in different chronic lung diseases." (PMID 34950829, 2021).
Cirrhosis (4 papers, 2013 to 2024). A chronic disorder of the liver in which liver tissue becomes scarred and is partially replaced by regenerative nodules and fibrotic tissue resulting in loss of liver function. "The presence of FGF23 mRNA in the context of cirrhosis was also observed on human and murine histology specimens in our study." (PMID 39525686, 2024). "Alcohol has been reported to induce upregulation of hepatic FGF23 and plasma FGF23 levels in patients with cirrhosis." (PMID 39062088, 2024). "We also observed hepatocyte and Kupffer cells induction of FGF23 mRNA as well as FGF23 protein production in mouse liver histology specimens of acute hepatitis, compared with cirrhosis and healthy liver." (PMID 39525686, 2024). "Other observations of moderate hepatic FGF23 production have been reported in other chronic contexts, such as cirrhosis or polycystic fibrosis." (PMID 39525686, 2024). "Histological data of acute hepatitis compared with cirrhosis and healthy liver confirmed our hypothesis of hepatic FGF23 overproduction." (PMID 39525686, 2024). "Furthermore, mouse models showed a significant increase in FGF23 mRNA relative liver expression in acute hepatitis and a moderate increase in cirrhosis, compared with healthy liver (respectively 60.55 ± 16.75 and 3.70 ± 0.87 vs 1.00 ± 0.65, both P < .05)." (PMID 39525686, 2024). "Although FGF23 mRNA is detected in fetal and adult liver alteration of its expression in cirrhosis or in liver injuries has not been studied so far." (PMID 23825530, 2013).
coronary artery stenosis (4 papers, 2013 to 2025). "We report an independent association between circulating FGF23 concentration and the severity and extent of coronary artery stenosis in the coronary angiographic patients." (PMID 24015259, 2013). "In conclusion, we report an independent association between circulating FGF23 concentration and the severity and extent of coronary artery stenosis in the coronary angiographic patients." (PMID 24015259, 2013). "First, as a cross-sectional study, the causal relationship between FGF23 concentration and the severity of coronary artery stenosis cannot be established." (PMID 24015259, 2013). "Supporting these findings, a positive correlation between FGF-23 serum levels and coronary calcifications, as well as the extent of coronary artery stenosis, has been previously identified." (PMID 40137447, 2025). "Thus it is plausible to infer that FGF23 could be involved in the process of vascular calcification, since vascular calcification is associated with coronary artery stenosis, which may help explain the association between elevated FGF23 and the severity of coronary artery stenosis." (PMID 24015259, 2013). "A cross-sectional design was used to examine the relationship between serum FGF23 and the severity and extent of coronary artery stenosis in 2076 patients undergoing coronary angiography (1263 male and 813 female, mean aged 62.5 years)." (PMID 24015259, 2013). "Serum FGF23 concentration was positively correlated with stenosis scores as the global index of the severity and extent of coronary artery stenosis in both male and female (r = 0.315 and r = 0.291, P<0.001)." (PMID 24015259, 2013). "In our patient population, FGF23 was significantly increased and associated with coronary stenosis independent of serum phosphorus level,which still remained within the normal range in majority of the population." (PMID 24015259, 2013).
coronary atherosclerosis (4 papers, 2014 to 2025). Atherosclerosis of the coronary vasculature. "Elevated serum FGF-23 levels have been found to be associated with vascular diseases such as CIMT, arterial stiffness, and coronary atherosclerosis in patients with advanced CKD." (PMID 30462803, 2018).
craniosynostosis (4 papers, 2019 to 2023). Craniosynostosis is defined as the premature fusion of one or more cranial sutures leading to secondary distortion of skull shape resulting in skull deformities with a variable presentation. "Serum FGF23 levels also correlated to mouse body measurements, the incidence of craniosynostosis, skull shape abnormalities and skull bone density and volume fraction." (PMID 35909501, 2022). "In other words, high levels of FGF23 correlated with poor skull bone, decreased body size, incidence of craniosynostosis and skull shape defects." (PMID 35909501, 2022). "In contrast, craniosynostosis in the form of coronal suture fusion had a moderately positive Spearman correlation with serum FGF23 levels (r = 0.47)." (PMID 35909501, 2022). "We also found strong positive correlation between serum FGF23 levels and craniosynostosis plus skull shape abnormalities." (PMID 35909501, 2022). "Beyond downregulation of TNAP, proposed mechanisms for these changes include TGF-β/BMP signalling (ERK1/2) and Wnt signalling, while cross-binding of FGF23 with FGFR2 and FGFR3 at the cranial sutures has also been proposed to contribute to craniosynostosis." (PMID 30808384, 2019). "Effects of blocking FGF23 on the development of craniosynostosis have not been reported at this stage." (PMID 30808384, 2019).
cystinosis (4 papers, 2017 to 2026). Cystinosis is a metabolic disease characterized by an accumulation of cystine inside the lysosomes, causing damage in different organs and tissues, particularly in the kidneys and eyes. "However, in cystinosis, FGF23 levels remain paradoxically low despite persistent hypophosphatemia from renal Fanconi syndrome." (PMID 40369127, 2026). "In another study, cystinosis patients with advanced CKD exhibited suppressed FGF23 levels, alongside high levels of bone turnover markers, highlighting a distinct mineral imbalance different from other forms of CKD and underscoring the need for cystinosis-specific management strategies." (PMID 40369127, 2026). "Only one patient of the patients with tubulopathy had cystinosis with advanced CKD and the FGF23 concentration was not outside of the expected range." (PMID 28659167, 2017).